CXCL12 (C-X-C motif chemokine ligand 12)
Diseases named in the same sentence as CXCL12 in open-access papers (continued):
Sharing a sentence is not in itself a finding about the gene and the disease.
cancer (continued). "CXC motif chemokine 12 (CXCL12) is a chemokine protein, also known as stromal cell-derived factor 1 (SDF-1), that provides cancer drug resistance and immune checkpoint inhibitor resistance." (PMID 39407665, 2024). "Our research supported these findings by demonstrating an increase in circulating levels of SDF-1 in cases of SCLC, further emphasizing CXCL12's role in cancer biology." (PMID 39132165, 2024). "CXCR4/CXCL12 axis is a promising therapeutic target for blocking the CXCL12/CXCR4 interaction and inhibiting downstream intracellular signaling for the treatment of various cancers." (PMID 39001265, 2024). "Our analyzis identified shared markers among the fibroblasts from both carcinoma types, notably DCN, VIM, ACTA2, CXCL12/14, and COL1A1, which were prominent markers, characteristic of these cells." (PMID 39796089, 2024). "CAF-mediated CXCL12 expression is critically involved in epithelial–mesenchymal transition (EMT), which enables cancer cells to acquire cancer stem cell (CSC) phenotype and tumorigenicity." (PMID 37966614, 2023). "CXCL12/CXCR4 axis is also responsible for mast cells recruitment from normal vasculature or healthy tissues, which turns it into a potential target for cancer therapies." (PMID 38313431, 2023). "On the contrary, the increased expression of CXCL12, a ligand for CXCR4, facilitates the escape of cancer cells from dormancy." (PMID 37173977, 2023). "Deletion of LPAR1 in MDA-MB-231 cells increased CXCL12-induced calcium flux and cell migration, indicating that LPA1 can inhibit CXCR4 in cancer cells expressing both receptors." (PMID 37749552, 2023). "The chemokine and receptor are expressed almost ubiquitously in human tissues and cells throughout life, and abnormal expression of CXCL12 and CXCR4 is observed in pathological conditions, such as inflammation and cancer." (PMID 37141381, 2023). "CXCL12, also referred to as stromal cell-derived factor-1 (SDF-1), enhances cancer cell metastasis via TGF-β1 secretion." (PMID 38004606, 2023). "The CXCL2, CXCL12, and CX3CL1 genes of this signature were shown to be significantly expressed in monocytes and cancer cells, according to scRNA-seq analysis." (PMID 37021054, 2023). "Protein expression of CXCL5/CXCR2 and CXCL12/CXCR4 were decreased with KT treatment, resulting in KT inhibiting cancer cells’ secondary growth within the bone." (PMID 36674719, 2023). "CAF-derived factors, such as matrix metalloproteinase 2 (MMP2), the chemokine CXCL12, TGF-β, and IL-6, facilitate the proliferation and invasion of cancer cells in various tumors." (PMID 37174001, 2023). "To explore the mechanism by which CXCL12 secreted by CAFs induces sorafenib resistance in HCC cells, we assessed two datasets of cancer cells treated with CXCL12 protein (GSE15893 and GSE40017) in the GEO database." (PMID 38057830, 2023). "The binding of CXCL12 to CXCR4 on cancer cells promotes their growth, survival, and migration, which contributes to cancer progression and metastasis." (PMID 37538932, 2023). "Its binding to roundabout guidance receptor 1 (ROBO1) can affect a variety of downstream pathways, such as β-catenin/LEF/TCF, PI3K/Akt, CXCL12/CXCR4 and RAFTK/Pyk2, and can regulate cancer invasion and metastasis." (PMID 37443302, 2023). "TGFβ inhibits an IL1-induced phenotype and drives the fibroblast to acquire a myofibroblastic phenotype with less carcinogenesis, including reduced expression of markers supporting cancer stemness, such as IL6 and CXCL12." (PMID 36672697, 2023). "If CXCL12 binds to CXCR4 expressed by DCs, the immune trafficking processes are triggered, but if it binds to CXCR4 present on cancer cells, the LN metastasis cascade begins." (PMID 37744339, 2023). "NOX-A12 is a pegylated L-type RNA aptamer resistant to nuclease degradation that binds to chemokine CXCL12, which plays an important role in the TMEN and cancer cell signaling." (PMID 37370863, 2023).
cancer (continued). "Of specific interest to this article, RNA therapeutics are also under development that aim to harmonize hyperinflammation (again in cancer), such as aptamer NOX-A12 and NOX-E36, which disrupt the expression of CXCL12 and CCL2, respectively." (PMID 37109050, 2023). "In cancer, the CXCR4 pathway, induced by the binding of its ligand CXCL12, was identified to promote metastasis and angiogenesis, and to regulate immune dysfunction." (PMID 37513979, 2023). "We compared the single-cell data of MDA-MB-231 cancer cells preconditioned with either 100 nM alpelisib, 10 nM trametinib, and 10 μM SB203580 two hours prior to the addition of a CXCL12 gradient." (PMID 36829763, 2023). "Either siRNA silencing or CRISPR-Cas9-based knockout of AHR prevented expression of CYP1A1, but amplified the expression of MMP9, CXCL12 and CXCR4 that contribute to the tumorigenesis and metastasis of the cancer cells." (PMID 37151890, 2023). "Considering the pivotal role of the CXCL12/CXCR4 axis in the complex TME, the development of targeted therapies aimed at disrupting this pathway is needed for efficient cancer treatment." (PMID 38004606, 2023). "CAFs can stimulate cancer growth and progression by secreting stromal cell-derived factor 1 (SDF-1)/C-X-C motif ligand 12 (CXCL12), transforming growth factor-β (TGF-β), interleukin (IL)-8, and IL-32." (PMID 36624542, 2023). "PDCD1, TGFB1, CXCL8, CCL3, CCL4, and CCL5 were highly expressed in subTME-IS; CXCL2 and CXCL12 were highly expressed in subTME-ICI, which was consistent among cancer types." (PMID 38002057, 2023). "KT alleviates the invasion of cancer cells from blood vessels to bone by inhibiting CXCL5/CXCR2 and CXCL12/CXCR4." (PMID 36674719, 2023). "CXCL12 derived from PAAD cells can induce SCs to infiltrate the tumor in the early canceration process and promote cancer cells to attract and migrate to the nerves." (PMID 36900158, 2023). "These included multiple ligands with previously supported roles in cancer cell invasion, including TGF-β1, IL-6, CXCL12, and MMP9, underscoring the robustness of our approach." (PMID 36881486, 2023). "Not only that, CAFs can also activate the Wnt/β-catenin pathway in EOC cells (mouse microglia) through the CXCL12/ CXCR 4-axis, resulting in cancer cells resistant to CDDP." (PMID 37666813, 2023). "Some drugs that target CXCR4 have been developed for cancer treatment, such as plerixafor (AMD3100), which prevents the binding of CXCL12 to CXCR4 and thus inhibits the growth and spread of cancer cells." (PMID 37538932, 2023). "As the CXCL12/CXCR4 axis mediates the interaction between stromal cells and cancer cells in TME, our study aimed to identify the therapeutic potential of curcumin by focusing on its inhibitory effect on breast TME." (PMID 38004606, 2023). "CXCL12 activates CXCR4 and CXCR7 chemokine receptors, and the signal axis is dysregulated in multiple types of cancer." (PMID 36639681, 2023). "The stromal cell-derived factor 1 (SDF-1), also known as C-X-C motif chemokine 12 (CXCL12), can facilitate macrophage recruitment during cancer progression." (PMID 36980785, 2023). "Increased levels of both CXCL12 and CXCR4 in cancer cells and the related microenvironment are frequently observed and are responsible for cell proliferation and metastasis, indicating their utility as cancer biomarkers." (PMID 37141381, 2023). "With regards to chemokines and chemokines receptors, our results revealed significantly positive correlations of HIC1 with CXCL12 and CCR10 in several cancers." (PMID 37388742, 2023). "This was associated with the reduced expression of the key regulators of B cell chemotaxis, Cxcl12 and Cxcl13 by both the HFD and the cancer cells." (PMID 38264656, 2023). "In adult human testes, CXCL12 is predominantly expressed by Sertoli cells, while CXCR4 is expressed by normal spermatogonial and meiotic germ cells, as well as most cancer cells." (PMID 36614308, 2023).
cancer (continued). "Tyrosine kinase Src is activated through the binding of CXCL12 to CXCR4, and downstream effector AKT improves the survival of cancer cells that occupy bone tissues." (PMID 36230523, 2022). "The expression levels of CXCL12, THBS1, PPBP, GZMB, CD74, and UNC93B1 were higher in the cancer group than in the normal group." (PMID 36211454, 2022). "Scavenging of CXCL12 by ACKR3 has also been shown to promote growth and metastasis of CXCR4+ breast cancer cells and is thought to contribute to the progression of other cancers." (PMID 35857509, 2022). "The additional observation that cancer cells in these tumors appeared to be “coated” with CXCL12, the ligand for CXCR4, suggested that the cancer cells have specifically adapted to the chemokine/chemokine receptor system." (PMID 35046049, 2022). "CAF-S1 stimulated cancer cell migration and mediated EMT transition through the activation of CXCL12 and TGF-β." (PMID 36185262, 2022). "ING5 suppresses aggressive phenotypes of various cancer cells via EGFR/PI3K/Akt, IL-6/STAT3, Akt/NF-κB/NF-κB/MMP-9 or IL-6/CXCL12 pathway." (PMID 36425530, 2022). "The nanoparticles blocked the interaction between cancer cells and stroma to interfere with cancer progression through blocking the binding between CXCR4 and C-X-C motif chemokine ligand 12 (CXCL12) with CXCR4 antagonists." (PMID 35875197, 2022). "CAF-S1 were found to promote cancer cell migration and epithelial-mesenchymal transition (EMT) by the CXCL12 and TGFβ pathways whereas CAF-S4 were found to promote cancer cell invasion, particularly in three-dimensional models through NOTCH signalling." (PMID 35479076, 2022). "COX2 inhibition blocks CXCL12 production in EOC and the ability to attract MDSC, reducing the immunosuppressive effect of cancer." (PMID 35269786, 2022). "CXCL12, the ligand of CXCR4, which is secreted from activated fibroblasts, was proven to stimulate cancer cell migration and promote cancer cell invasion through EMT transition, and is also elevated in CAF1 compared to NF1/NF2." (PMID 35853880, 2022). "Chemokine receptors are expressed by different cancer cells and up-regulation of chemokine-receptor pairs (e.g. (Stromal cell-derived factor 1 (SDF-1/CXCL12)/C-X-C chemokine-receptor type 4 (CXCR4)) promotes metastasis." (PMID 35015084, 2022). "M2 macrophages (C6-Mye) were predicted to secrete the factors CXCL12 and CCL4 to attract CD8+ Tex cells by binding to CXCR3/CXCR4 and CCR5 on CD8+ Tex cells, which are known to recruit immunocytes into cancer tissues." (PMID 35562760, 2022). "Once the chemokine CXCL12 is tethered to the CXCR7 receptor, it activates divergent pathways leading to significant alterations in cancer cell survival, proliferation, and migration." (PMID 35408440, 2022). "Luciferase complementation data showing the CXCL12-dependent dissociation of PKM2 oligomers suggested that CXCR4 and ACKR3 signaling shifted cancer cells toward glycolysis." (PMID 35681470, 2022). "Stromal-cell derived factor-1 (SDF-1) which is also known as CXCL12, in the TME of malignant tumors and high expression of CXCL4 ligand results in the accumulation of DCs in TME." (PMID 36303138, 2022). "Among these, there is growing interest in the role of CXCL12, CXCR4, and FAPα expression in cancer because of their immunosuppressive and procancer properties 50-52." (PMID 34976180, 2022). "Our team discovered that cancer-originated DNA can activate the CXCL12-CXCR4 and CCL21-CCR7 axes in HCC cells, while sinoline treatment reduced the expressions of CXCL12, CXCR4, CCL21, and CCR7 in HCC cells." (PMID 35860597, 2022). "CXCR4 is a marker of normal and malignant stem cells, and CXCL12/CXCR4 signaling is a crucial regulator of stem cell trafficking and cancer cell metastasis." (PMID 36591565, 2022). "CXCL12, binding to its receptor CXCR4, has been reported to be related to the prognosis of several types of cancer and promote cancer progression in preclinical models, including IBD and CRC." (PMID 35363937, 2022).
cancer (continued). "Another promising target is CXCR4, the receptor for SDF-1/CXCL12, which is expressed in CAFs, MDSCs and cancer cells." (PMID 36436127, 2022). "To test the effects of UBE2T, TK1, CXCL12, and KPNA2 on cancer cell invasion, we knocked down these genes in murine CAFs via siRNAs." (PMID 35884546, 2022). "Preclinical studies proved that blocking the CXCR4/CXCL12 axis with plerixafor (AMD3100), CXCR4-specific peptides, or monoclonal antibodies reduced cancer growth and metastasis while promoting sensitization to chemotherapy, radiation, or immunotherapy." (PMID 35336029, 2022). "This is due to CAFs regulate C-X-C motif chemokine ligand 12 (CXCL12) secretion and ECM deposition, preventing physical contact between T cells and cancer cells.." (PMID 36338755, 2022). "Under the hypoxic conditions prevalent in cancer, hypoxia-inducible factor (HIF)-1α selectively enhances CXCR4 expression and chemotactic responses to CXCL12—including EOC cells, TAMs, and endothelial cells—thus inducing angiogenesis." (PMID 35269786, 2022). "In most cancers, CD86, TNFSF14, KLRK1, CD48, CD40LG, CD28, C10orf54, ENTPD1, CXCL12, and POLD2 are negatively correlated (p < 0.05)." (PMID 36081989, 2022). "There was a significant correlation of the CXCL12 levels in plasma membrane expression and CXCR4 and FAPα levels in the cancer cells of LARC after nCRT group (Spearman's Rho: p = 0.001 and p = 0.003)." (PMID 34976180, 2022). "CXCL12 acts via CXCR4 and ACKR3 receptors, which are significantly expressed on the cancer cell surface." (PMID 35743888, 2022). "Specifically, DARC internalizes CXCL12, which signals via the CXCL12/CXCR4 axis, to promote migration and metastasis of cancer cells." (PMID 36497078, 2022). "The enhanced expression of CXCL12, HGF, MMPs, and TGF-β in irradiated fibroblasts was found to increase invasion and EMT in cancer cells as indicated by the increased expression of vimentin, snail and beta-catenin, and decreased E-cadherin expression." (PMID 36010899, 2022). "These are noteworthy that CXCL12 and EPB41L3 were verified by the GEPIA in COAD and READ cancer types while SCNN1B and PYY were documented only in COAD cancer type by the GEPIA." (PMID 35333898, 2022). "An increase in mRNA expression of CXCL12, CXCR4, and FAPα was observed in residual cancer tissues after nCRT treatment." (PMID 34976180, 2022). "Follow-up transcriptomic profiling unearthed a potential mechanism of communication, mediated by PDGF and CXCL12, between ALK+ cancer cells, endothelial cells, and pericytes." (PMID 36192379, 2022). "Broad parallels drawn between cancer and PAH provided apt justification for the study of mechanisms controlling CXCL12 in PAH." (PMID 36670936, 2022). "Current advances in cancer biology have highlighted the crucial role of CXCR4 receptor and its respective ligand CXCL12, in the metastasis of different kinds of cancer." (PMID 35250573, 2022). "Together with its ligand CXCL12, CXCR4 plays critical role in cancer progression especially metastasis." (PMID 36230825, 2022). "The interactions between CXCL12 and CXCR4 or CXCR7 comprise a biological axis that affects the growth, angiogenesis, and metastasis of cancers." (PMID 35079936, 2022). "SDF-1/CXCL12 is the primary secretome of CAFs, which promotes cancer growth by interacting with CXCR4 in cancer cells." (PMID 36042526, 2022). "The CXCL12/CXCR4 axis has been identified as a target for drug development in oncology due to its critical role in promoting and maintaining cancer stem cells." (PMID 36140541, 2022). "Since stromal-vascular BM niches secrete abundant CXCL12, whereas CXCR4 is primarily expressed on HSCs and malignant cells, the CXCL12/CXCR4 axis becomes a key pathway for both normal hematopoiesis and cancer cell homing to the BM." (PMID 36428753, 2022). "Cancer cell proliferation is stimulated by MSC-derived chemokines CXCL1/2 and CXCL12/SDF-1 that activate signaling pathways dependent on respective CXCR2 and CXCR4 receptors expressed by cancer cells." (PMID 35269887, 2022).
cancer (continued). "Changes in CXCL12 and CXCR4 levels in pre-nCRT biopsy and paired post-nCRT surgical specimen tissue samples from 45 LARC patients showed higher expression in LARC cancer cells after nCRT (p < 0.001 for each, Wilcoxon signed-rank test)." (PMID 34976180, 2022). "CAFs can promote the immunosuppression of cancer cells by secreting TGF-β, IL-6, CXCL12 and CCL2, thereby preventing cytotoxic T cell activity and recruiting immunosuppressive populations." (PMID 36185262, 2022). "The dysregulation of significant cancer-related genes (FAM83H, CXCL12, PITPNA, HMOX1, DGKZ, NR5A2, VMP1, and ID1) was confirmed by qRT-PCR." (PMID 36232920, 2022). "Neoplastic CXCR4 and CXCL12 discriminated PDACs for recurrence-free survival (RFS), while CXCL12 and CXCR7 discriminated patients for cancer-specific survival (CSS)." (PMID 36359736, 2022). "Our previously published work in OPMD that dealt with cancer stem cells and markers of chemokine pathways indicated that the presence of CXCL12 (SDF-1) and CXCR4 in oral premalignant and malignant sections correlated with disease progression." (PMID 36009387, 2022). "One very prominent factor of this cancer cell homing is CXC motif chemokine 12, also known as CXCL12 or SDF-1, produced by bone marrow stromal cells and osteoblasts, which was proven to be crucial to metastases." (PMID 36230523, 2022). "MSCs and FBs ease the pathogenetic interaction between PCs and BMME via the excretion of CXCL12 (CXCR4 ligand, expressed on ECs and malignant PCs), which is relevant in the “cancer immunoediting” process." (PMID 35566637, 2022). "USP17 is induced by the stromal cell-derived factor-1 (SDF-1)/C-X-C motif chemokine ligand 12 (CXCL12) and IL-8/CXCL8 chemokines in cancer cells." (PMID 34454495, 2021). "Numerous studies using cancer and primary cells have shown that CXCR7 is a functional receptor in various cell types, although each contribution of CXCR7 or CXCR4 to CXCL12-mediated cell migration is still controversial." (PMID 34527817, 2021). "Among receptors of CXCL12, CXCR4 can specifically bind to CXCL12 and the role of CXCL12/CXCR4 axis is most broadly explored in cancers." (PMID 33747959, 2021). "TLS in other cancers have been identified and defined by expression of a number of chemokines that are involved in TLS neogenesis: CCL19, CCL21, CXCL12, CXCL13, CCL17, and CCL22." (PMID 34943886, 2021). "In the PDAC model, inhibition of CAF-mediated CXCL12/CXCR4 axis with the CXCR4 inhibitor AMD3100 promoted T-cell accumulation and cancer regression." (PMID 33859752, 2021). "The increased expression levels of CXCL12 and CXCR4 detected by immunohistochemistry in cancer tissues were 50%–78% and 61%–80%, respectively, showing significantly higher levels than found in the corresponding normal tissues." (PMID 33710803, 2021). "High CXCL12/SDF-1 level is seen in metastatic lymph nodes and CXCR4 upregulation in cancer cell lines exposed to pDC conditioned media." (PMID 34337083, 2021). "The secretion and production of chemokines such as CCL2, CXCR1/2, CXCL12, CXCR4, and CXCL8 play critical roles in cancer development and subsequent metastasis." (PMID 34530822, 2021). "CXCL12 signaling inhibition synergizes with immune checkpoint blockade by PD-1 and CTLA-4 antibodies in mouse cancer models." (PMID 33753872, 2021). "Numerous studies have since described CXCL12 in a wide variety of processes and diseases such as HIV, rheumatoid arthritis, asthma, amyotrophic lateral sclerosis, and cancer." (PMID 33530455, 2021). "This overexpression guides TAMs along the CXCL12 gradient produced by perivascular CAFs, resulting in the acquisition of a perivascular TAM phenotype that induced vascular leaks and facilitated cancer cell migration." (PMID 33530455, 2021). "The activation of CXCL12 and its receptor CXC chemokine receptor 4 (CXCR4) signaling has been shown to promote cancer cell growth and metastasis in various types of cancers." (PMID 34071280, 2021).